SOX2 (SRY-box transcription factor 2)
Description:
Transcription factor that forms a trimeric complex with OCT4 on DNA and controls the expression of a number of genes involved in embryonic development such as YES1, FGF4, UTF1 and ZFP206 (By similarity). Binds to the proximal enhancer region of NANOG (By similarity). Critical for early embryogenesis and for embryonic stem cell pluripotency. Downstream SRRT target that mediates the promotion of neural stem cell self-renewal (By similarity). Keeps neural cells undifferentiated by counteracting the activity of proneural proteins and suppresses neuronal differentiation (By similarity). May function as a switch in neuronal development (By similarity).
Synonyms: ANOP3; MCOPS3
Tractability: Small molecule: a structure with a bound ligand is known. PROTAC: UniProt records ubiquitination sites on it; ubiquitination databases record sites on it.
Gene: Protein-coding gene on chromosome 3 (181,711,925 to 181,714,436, forward strand). Ensembl gene ENSG00000181449.
Subcellular location: Nucleus speckle; Cytoplasm; Nucleus
Subcellular location (Human Protein Atlas): Nucleoplasm
Pathways (Reactome):
Developmental Biology: Formation of the anterior neural plate; Formation of the posterior neural plate; Germ layer formation at gastrulation; POU5F1 (OCT4), SOX2, NANOG activate genes related to proliferation; POU5F1 (OCT4), SOX2, NANOG repress genes related to differentiation; Regulation of MITF-M-dependent genes involved in extracellular matrix, focal adhesion and epithelial-to-mesenchymal transition; Specification of the neural plate border; Transcriptional and post-translational regulation of MITF-M expression and activity; Transcriptional regulation of pluripotent stem cells
Immune System: Interleukin-4 and Interleukin-13 signaling
Signal Transduction: Deactivation of the beta-catenin transactivating complex
Gene Ontology:
Molecular function: DNA binding; DNA-binding transcription factor activity; miRNA binding; protein binding; sequence-specific DNA binding; transcription cis-regulatory region binding; DNA-binding transcription activator activity, RNA polymerase II-specific; DNA-binding transcription factor activity, RNA polymerase II-specific; RNA polymerase II cis-regulatory region sequence-specific DNA binding
Biological process: endodermal cell fate specification; eye development; forebrain development; inner ear development; negative regulation of canonical Wnt signaling pathway; negative regulation of cell cycle G1/S phase transition; osteoblast differentiation; pituitary gland development; positive regulation of DNA-templated transcription; positive regulation of MAPK cascade; positive regulation of transcription by RNA polymerase II; regulation of DNA-templated transcription; regulation of gene expression; response to growth factor; response to wounding; somatic stem cell population maintenance; brain development; chromatin organization; glial cell fate commitment; negative regulation of neuron differentiation; negative regulation of transcription by RNA polymerase II; neuron differentiation; neuronal stem cell population maintenance
Cellular component: cytoplasm; cytosol; nucleoplasm; nucleus; chromatin; nuclear speck; transcription regulator complex
Genetic constraint (gnomAD): Loss-of-function variants: 2 observed, 20.88 expected, observed/expected ratio (o/e) 0.0958, 90% interval 0.038 to 0.3. The upper end of that interval is the gene's LOEUF score, 0.3, which puts it in group 1 of 6, group 1 being the genes least tolerant of losing a copy. Missense variants: 294 observed, 470.89 expected, observed/expected ratio (o/e) 0.62, 90% interval 0.57 to 0.69. Synonymous variants: 211 observed, 204.01 expected, observed/expected ratio (o/e) 1.03, 90% interval 0.92 to 1.16.
Cancer hallmarks: suppression of growth (promotes); proliferative signalling (promotes); angiogenesis (promotes); escaping programmed cell death (suppresses); escaping immune response to cancer (promotes); cell replicative immortality; escaping immune response to cancer; invasion and metastasis (suppresses); escaping programmed cell death (promotes); invasion and metastasis (promotes); change of cellular energetics (promotes); genome instability and mutations (suppresses); tumour promoting inflammation
Homologues: Orthologues: chimpanzee SOX2 (99% identical), pig SOX2 (99% identical), mouse Sox2 (98% identical), rat Sox2 (98% identical), tropical clawed frog sox2 (86% identical), zebrafish sox2 (86% identical), Drosophila melanogaster Sox21a (40% identical), Caenorhabditis elegans sox-2 (36% identical), Caenorhabditis elegans sox-3 (32% identical), Drosophila melanogaster Sox14 (29% identical). Paralogues in human: SOX1 (63% identical), SOX3 (60% identical), SOX14 (36% identical), SOX21 (35% identical), SOX15 (32% identical), SOX9 (27% identical), SOX6 (26% identical), SOX18 (26% identical), SOX10 (25% identical), SOX11 (25% identical), SOX8 (24% identical), SOX4 (24% identical), and 8 more.
Diseases named in the same sentence as SOX2 in open-access papers:
SOX2 is named in the same sentence as 527 diseases in open-access papers, as found by Europe PMC text mining. Sharing a sentence is not in itself a finding about the gene and the disease. The quoted sentences say what the papers report.
breast cancer (557 papers, 2009 to 2026). A primary or metastatic malignant neoplasm involving the breast. "SOX2 is not only implicated in the initiation, progression, invasion, and metastasis of breast cancer but also plays a significant role in its recurrence and resistance." (PMID 39976818, 2025). "Further, to validate possible association of the YAP/TAZ/SOX2 interactome with breast cancer stemness, ALDH+ and ALDH− cell populations from patient breast tissues and mice mammary tissues were analyzed." (PMID 39979255, 2025). "This study aimed to verify the biologic role of SOX2OT associated with SOX2 in tamoxifen-resistant breast cancer and to understand the potential relationship between TME and lnRNA SOX2OT." (PMID 38649821, 2024). "Several studies associated the Notch pathway as well as SOX2 with features of cancer stem cells and resistance to chemotherapy in breast cancer." (PMID 39478150, 2024). "Some CSC features such as the tumor-initiating capacity, and high OCT4, and SOX2 expression have been associated with malignancy and a worse prognosis in canine mammary tumors." (PMID 38672378, 2024). "One of the lncRNA, SOX2 has been identified in 43% of basal cell-like breast cancers, and it is significantly associated with CK5/6, EGFR, and vimentin immunoreactivity, while showing an inverse association with estrogen and progesterone receptor status." (PMID 38649821, 2024). "In breast cancer (BC), SOX2 contributes to tumour malignancy and causes cells to display stromal-like features." (PMID 38494478, 2024). "In breast cancer, transcriptional programs associated with stemness core transcription factors, such as Oct4, Nanog and Sox2, promote EMP and, reciprocally, EMT transcription regulators influence stem cell characteristics." (PMID 37345027, 2023). "High Sox2 expression is observed in nearly half of the basal cell-like breast carcinomas and is associated with sphere-formation ability and CSC proliferation." (PMID 37853437, 2023). "In the present study, OCT4 and SOX2 expression was upregulated in patients with breast cancer and was associated with an increased TNM stage, poor differentiation, and poor prognosis." (PMID 35402219, 2022). "SOX2, Nanog, and Oct4 expression was associated with poor differentiation, advanced cancer stages, and the worst outcomes in breast cancer patients." (PMID 36077806, 2022). "In luminal FMCs, a positive association was observed between Sox2 expression and higher histological grades, in agreement with numerous reports in breast cancers." (PMID 33553286, 2020). "We then extracted breast cancer date sets from the Molecular Taxonomy of Breast Cancer International Consortium (METABRIC) to explore the association between SOX2 expression and multiple breast cancer subtypes." (PMID 32191225, 2020). "In breast cancers, Sox2 expression has been associated with poor prognosis, and resistance to therapy." (PMID 33553286, 2020). "In breast cancers also, which are luminal in approximately 70% of the cases, Sox2 has been positively associated with tumor size in consecutive series and a meta-analysis." (PMID 33553286, 2020). "Binding sites for miR-140 miR-9 and miR-132: By targeting the 3’ UTR of mRNA and annealing at nucleotide position 2078–2100, miR-140 is implicated in downregulating SOX2 expressions in breast cancer." (PMID 32092088, 2020). "A SOX2 SNP, rs11915160, at chr3:181713783 (A > C) evaluated for susceptibility to breast cancer was detected in exosomal SOX2 DNA of GBM, and GBM stem cells." (PMID 33137926, 2020). "Sox2-positive breast cancers have been associated with poor disease-free survival, and poor overall survival." (PMID 33553286, 2020). "Targeting the MUC1 cytoplasmic domain (MUC1-C) genetically or pharmacologically decreased: (i) expression of breast cancer stem cell markers including SOX2; and (ii) lung cancer stem cell generation associated with decreased levels of SOX2." (PMID 32793510, 2020).
breast cancer (continued). "Clinical-pathologic associations with Sox2 expression expressed as an index in feline mammary carcinomas (N = 180)." (PMID 33553286, 2020). "In conclusion, we report here that the stem cell pluripotency factor Sox2 is commonly expressed in feline mammary carcinomas, is associated with higher proliferation, decreased PR and FOXA1, but higher AR expression, as well as poor outcomes." (PMID 33553286, 2020). "Understanding the mechanisms underlying Sox2 overexpression would be a prerequisite before setting eventual Sox2-targeted clinical trials in feline mammary carcinoma patients." (PMID 33553286, 2020). "Clinical-pathologic associations with Sox2 expression evaluated at >42% cutoff in feline mammary carcinomas (N = 180)." (PMID 33553286, 2020). "Accordingly, decreased expression of SOX2 is significantly associated with decreased angiogenesis and lymphangiogenesis in breast cancer." (PMID 31244283, 2019). "Subsequently, we compared the expression of stem cell-associated proteins Nanog, OCT4, and SOX2 proteins in normal breast cancer cell lines and microspheres." (PMID 30906504, 2019). "Sox2 has been implicated in breast cancer as it is overexpressed in mammary tumors and responsible for BCSC function." (PMID 30388742, 2018). "Specifically, the Wnt5 and Sox2 genes were implicated in the digit development but also in oncogenesis of breast cancer, prostate cancer, gliomas, and gastric cancer." (PMID 29581795, 2018). "SOX2 has also been implicated in endocrine resistance in breast cancer and in the development of chemo-resistance in gastric cancer, glioblastoma, head and neck squamous cell carcinoma, lung cancer, and prostate cancer." (PMID 28929082, 2017). "Linc00617 is another lncRNA upregulated in breast cancer and its overexpression is associated with an increased breast cancer CSC fraction via upregulation of SOX2." (PMID 28430163, 2017). "Our results suggest that high levels of SOX2 protein are associated with poor prognosis of breast cancer." (PMID 28288641, 2017). "Here, we observed a positive association of FGFR1 with the transcriptional factor SOX2 with neural stem cell renewal, and particularly with neuroendocrine differentiation in breast cancer." (PMID 26673008, 2016). "A similar approach was used in breast cancer where early stages of carcinogenesis were linked with Sox2 expression." (PMID 27766946, 2016). "Inhibition of miR-140 allows for uncontrolled elevation of SOX2, which is known to be a stem cell self-renewal regulator causing an increase in stem cell populations and breast cancer progression, initiation and growth." (PMID 27502506, 2016). "Previously, we reported the specific association of SOX2 with expression of hormonal receptor and neuroendocrine differentiation in breast cancers." (PMID 26673008, 2016). "High expression levels of SOX2OT and SOX2 are associated with estrogen receptor status and tamoxifen sensitivity of breast cancer cells." (PMID 26136768, 2015). "In this study we utilized a programmable DNA-binding methyltransferase to induce targeted incorporation of DNA methylation (DNAme) in the SOX2 oncogene in breast cancer through a six zinc finger (ZF) protein linked to DNA methyltransferase 3A (ZF-DNMT3A)." (PMID 25684141, 2015). "Overexpression of SOX2 has been implicated in the regulation of mammosphere formation in the breast cancer model." (PMID 25897700, 2015). "New technologies, such as engineered zinc finger-based artificial TFs, have been constructed to selectively silence SOX2 gene expression in breast cancer cell lines, causing SOX2 mRNA downregulation and reducing cell proliferation and colony formation." (PMID 26580604, 2015). "Similar to gliomas, breast carcinomas overexpress SOX2, and this is associated with high rates of cell proliferation, tumourigenesis and pathological grade." (PMID 26580604, 2015). "Sox2, a transcription factor and an embryonic stem cell marker, has been implicated in the pathogenesis of breast cancer (BC)." (PMID 24885403, 2014).
breast cancer (continued). "It has been reported that SOX2 expression is associated with the promotion of tamoxifen resistance in breast cancer, and that ectopic expression of SOX2 contributes to tamoxifen resistance in the MCF-7 breast cancer cell line." (PMID 25006803, 2014). "While mechanisms controlling its role in bronchiolar cell proliferation are unclear at present, Sox2 promotes proliferation in breast cancer cell lines and the loss of Sox2 promotes terminal differentiation of neuronal stem cells." (PMID 20011520, 2009). "Moreover, SOX2OT has been identified as a novel biomarker linked to tamoxifen-resistant breast cancer, and its association with SOX2 has also been documented." (PMID 38649821, 2024). "It was also able to reduce the expression of c-Myc, Sox-2, and Oct4, which are stemness-associated proteins, in breast cancer cells and to decrease the proportion of CD44+/CD24− breast cancer stem cells in the tumor population, thus inhibiting tumor progression." (PMID 37894640, 2023). "Interestingly, Salinivenus iranica SMs significantly reduced the number and size of spheres and colonies in all breast cancer cell lines, which were associated with the downregulation of SOX2 as a pluripotency gene." (PMID 37542193, 2023). "Interestingly, SALL4 associates with Nanog, OCT4, and Sox2 to enable breast cancer cells to acquire stem‐cell‐like and metastatic properties." (PMID 34476264, 2021). "The long non‐coding RNA SOX21‐AS1 has been previously reported to modulate the properties of breast cancer stem cells via targeting SOX2, although the underlying molecular mechanisms remain unclear." (PMID 33103351, 2021). "SOX2 expression has been reported to associate with the malignancy of tumors in breast cancer." (PMID 30517668, 2020). "Indeed, ATFs that bind to the proximal SOX2 promoters were shown to cause ~95% reduction of endogenous SOX2 mRNA and protein in breast cancer cells upon retrovirus-based delivery." (PMID 31748974, 2020). "Interestingly in human breast cancers, with cutoffs of ≥1% or ≥10% generally used for ER and PR, Sox2 associations also tend to differ between luminal and triple-negative breast cancers." (PMID 33553286, 2020). "We isolated the compound 6-methoxymellein, which inhibits the proliferation and migration of breast cancer cells, reduces mammosphere growth, decreases the proportion of CD44+/CD24− cells in breast cancer cells and decreases the expression of stemness-associated proteins c-Myc, Sox-2 and Oct4." (PMID 32977636, 2020). "The first objective of this study was to determine the frequency of Sox2 expression in feline mammary carcinomas, and its associations with clinical-pathologic features such as the clinical stage, histological grade, proliferation index, and hormone receptor expression." (PMID 33553286, 2020). "Also, resveratrol inhibited activation of AKT and STAT3 promoted by CAFs, thereby suppressing the expression of downstream molecules (CD44 and Sox2) associated with self-renewal in human breast cancer cells (T74D cells)." (PMID 30791624, 2019). "In addition, we found up-regulation of Slug, which is an upstream regulator of SOX2; expression of Slug is associated with basal-like breast cancer." (PMID 29552303, 2018). "Moreover, SOX2 expression has been linked to tamoxifen resistance and relapse in breast cancer treatment." (PMID 28288641, 2017). "Interestingly, the transcription factor SOX2 has recently been associated with breast cancer formation and metastasis." (PMID 28288641, 2017). "High levels of SOX2 proteins have been linked to breast cancer metastasis." (PMID 28288641, 2017). "However, other studies revealed that SOX2 expression was associated with subtypes and tumour grades of breast cancer." (PMID 28288641, 2017). "Furthermore, in breast cancer patients the prevalence of SOX2 antibodies was associated with higher tumor grade and positive nodal status." (PMID 25143958, 2014).